LRCH2 (leucine rich repeats and calponin homology domain containing 2)
Description:
May play a role in the organization of the cytoskeleton.
Synonyms: KIAA1495; dA204F4.4
Tractability: Antibody: the Human Protein Atlas places it where antibodies can reach. PROTAC: its protein half-life has been measured.
Gene: Protein-coding gene on chromosome X (115,110,616 to 115,234,096, reverse strand). Ensembl gene ENSG00000130224.
Subcellular location (Human Protein Atlas): Plasma membrane
Gene Ontology:
Molecular function: protein binding
Homologues: Orthologues: chimpanzee LRCH2 (99% identical), macaque LRCH2 (99% identical), pig LRCH2 (96% identical), guinea pig LRCH2 (93% identical), mouse Lrch2 (93% identical), rat Lrch2 (93% identical), rabbit LRCH2 (92% identical), dog LRCH2 (84% identical), tropical clawed frog lrch2 (72% identical), zebrafish lrch2 (58% identical). Paralogues in human: LRCH1 (43% identical), LRCH3 (42% identical), LRCH4 (33% identical), LRRK1 (23% identical), SCRIB (18% identical), ERBIN (17% identical), PHLPP1 (16% identical), LRRC7 (15% identical), PHLPP2 (14% identical), PIDD1 (13% identical), LRRC28 (13% identical), MFHAS1 (12% identical), and 19 more.
Diseases named in the same sentence as LRCH2 in open-access papers:
LRCH2 is named in the same sentence as 5 diseases in open-access papers, as found by Europe PMC text mining. Sharing a sentence is not in itself a finding about the gene and the disease. The quoted sentences say what the papers report.
breast carcinoma (1 paper, 2021). "LRCH2 expression was related with tumorigenesis, and over-expression of the gene involved in several carcinogenesis, including low grade of melanomas and gliomas, while LRCH2 gene expression was decreased in late stage breast cancer patients with metastasis." (PMID 34440082, 2021).
LRCH2 also shares sentences with these, for which no sentence is quoted: atherosclerosis (1 paper); glioma (1); lung carcinoma (1); melanoma (1).